SPARC (secreted protein acidic and cysteine rich)
Diseases named in the same sentence as SPARC in open-access papers (continued):
Sharing a sentence is not in itself a finding about the gene and the disease.
pancreatic cancer (continued). "Methylation of the SPARC gene, specifically CpG Region 2, may be an early event during pancreatic tumorigenesis and should be further evaluated as a tumorigenesis marker for early detection of pancreatic cancer." (PMID 20338068, 2010). "The SPARC gene may play a role in suppression of tumorigenesis, including pancreatic cancer." (PMID 20338068, 2010). "The analysis lead to the identification of TIMP-1, FN-1, SPARC, IGFBP-3, LGALS3BP, and GREM1 as the most upregulated glycoproteins in early-stage pancreatic tumor tissues as compared to controls." (PMID 40345589, 2025). "In pancreatic cancer, RUNX2 has been shown to regulate the transcriptional activity of the extracellular matrix proteins SPARC and MMP1, thereby influencing the tumor microenvironment." (PMID 40386045, 2025). "It was disclosed that upregulation of miR‐148b and‐152 led to the restoration of DNA methylation patterns to their normal states and facilitated TSGs re‐expression, such as SPARC and BNIP3 in pancreatic cancer cell lines (AsPC‐1 and MIA PaCa‐2)." (PMID 40387409, 2025). "In pancreatic cancer with a high ETV1 expression, the matricellular protein SPARC and the Hyaluronan Synthase 2 are two ETV1‐downstream targets responsible for its role in invasion and metastasis." (PMID 40275610, 2025). "Transfection of miR-148b or miR-152 in pancreatic cancer cells reactivated tumor suppressor genes such as BNIP3, SPARC, PENK, and TFPI-2 by downregulating DNMT1." (PMID 36959680, 2023). "First, we have analyzed in cfDNA from eight mPDAC patients the methylation levels of five genes BMP3, NPTX2, SPARC, TFPI2 and SFRP1 known to be aberrantly methylated in pancreatic cancer." (PMID 37481552, 2023). "For example, the genes SPARC, UCHL1, NPTX2, PENK, and PDAC were investigated in pancreatic cancer, where they were found to be hypermethylated in patients with pancreatic cancer." (PMID 34771655, 2021). "Transcription of the SPARC gene was higher in stroma fibroblasts (IVP-9TS) and lung cancer cells (Calu-1), compared to pancreatic cancer cell lines." (PMID 33804861, 2021). "Methylation of the SPARC gene TRR gradually increased from normal, chronic pancreatitis, and the adjacent normal tissues to pancreatic cancer tissues." (PMID 20338068, 2010). "Runx2 – in turn – suppresses the transcription of extracellular matrix modulators such as SPARC and MMP1, and thereby influences the pancreatic cancer microenvironment." (PMID 17876328, 2007). "Despite the relatively low efficiency of Runx2 silencing in the tested cell lines, there was a significant change in the expression of several target genes such as SPARC and MMP1 in IPSCs and Panc-1 pancreatic cancer cells." (PMID 17876328, 2007). "SPARC is markedly overexpressed and localised in fibroblasts and extracellular matrix surrounding tumour cells in PDAC, and increases the invasiveness of pancreatic cancer cells." (PMID 17876328, 2007). "Furthermore, miR‐148b and‐152, by regulating the expression of SPARC and BNIP3, play a crucial role in pancreatic cancer pathogenesis." (PMID 40387409, 2025). "To dissect the stromal and neoplastic compartment, we further generated primary CAF lines (n=2) from murine pancreatic tumours as well as PSCs (n=3) from healthy B6 mice showing typical spindle-shaped morphology, and strong expression of α-SMA, SPARC and fibronectin." (PMID 28077438, 2018). "In contrast to SPARC, FSTL1 was recently shown to inhibit pancreatic cancer growth." (PMID 29435136, 2018). "In direct contrast to SPARC, however, FSTL-1 expression is reduced in pancreatic cancer." (PMID 27886258, 2016). "We showed previously that orthotopic pancreatic tumor growth of Pan02 cells is more invasive and metastatic in the absence of host SPARC and that this confers a decrease in the survival of Sparc-null (SPARC−/−) mice relative to wild-type (SPARC+/+) littermates." (PMID 22348081, 2012).
pancreatic cancer (continued). "In the present study, we sought to determine the mechanism by which lack of host SPARC alters the tumor microenvironment and enhances invasion and metastasis of an orthotopic model of pancreatic cancer." (PMID 22348081, 2012). "The abundance of SPARC on pancreas cancer cells and matrix fibroblast varies with tumors often losing SPARC expression due to epigenetic changes; this does not appear to be the case with fibroblasts." (PMID 22016635, 2011). "Gene expression profiling using oligonucleotide microarray and reverse transcription-PCR analyses demonstrated that SPARC mRNA was expressed in non-neoplastic pancreatic ductal epithelial cells but not in the majority of pancreatic cancer cell lines." (PMID 20338068, 2010). "Conversely, co-administration of HMEC-1 cells enhanced the oncolytic efficacy of Ad(I)-F512-TK on SPARC-negative MIA PaCa-2 pancreatic cancer cells in vivo." (PMID 19337591, 2009). "This suggests that SPARC promoter was partially active on pancreatic cancer despite the lack of SPARC expression." (PMID 19337591, 2009). "It was not unexpected that the present CRAds were also slightly effective on SPARC-negative pancreatic cancer cells." (PMID 19337591, 2009). "After conducting a thorough analysis of published studies on cfDNA methylation in pancreatic cancer, as well as a comparative methylation analysis using the TCGA database, we have identified a set of consistently reported hypermethylated genes: BMP3, NPTX2, SFRP1, SPARC, and TFPI2." (PMID 37481552, 2023). "SPARC mRNA is expressed in nonneoplastic pancreatic ductal epithelial cells but is not found in pancreatic cancer cell lines, which indirectly indicates that the silencing of the SPARC gene can lead to the development of pancreatic cancer." (PMID 35211625, 2022). "Of note, SPARC is a very interesting ECM protein that, depending on cancer type, can promote (glioblastomas, melanoma, breast cancer and prostate cancer) or inhibit (neuroblastoma, ovarian cancer, pancreatic cancer, colorectal cancer and gastric cancer) metastasis." (PMID 34298680, 2021). "In a tumor model of pancreatic carcinoma, the absence of host SPARC promoted disruption of the vascular basement membrane, inhibition of pericyte recruitment, and reduction of MVD, resulting in enhanced vascular permeability and tumor supply by oxygen and nutrients for invasion and metastasis." (PMID 34209679, 2021). "Based on that, we assessed whether the present CRAd may be active on SPARC-negative pancreatic cancer cells in vivo in the presence or not of co-administered stromal cells." (PMID 19337591, 2009). "In colorectal cancer, the change in SPARC expression follows a similar pattern as in pancreatic cancer: higher levels of SPARC are observed in normal pancreatic ductal epithelial cells while it is absent in the majority of pancreatic cancers." (PMID 18458674, 2008). "In addition, three hub genes (SPARC, COL6A3, and FBN1) may also play a vital role in the microenvironment of pancreatic cancer through the regulation of tumor-infiltrating immune cells, suggesting they could serve as potential therapeutic targets for the modulation of the antitumor immune response." (PMID 32934754, 2020). "Therefore, the observed low-to-absent SPARC expression levels in some pancreatic cancer cells in vivo might be due to suppressive effects of Runx2." (PMID 17876328, 2007). "In resected pancreatic cancer, SPARC stromal and cytoplasmic overexpression was associated with statistically significant worse disease-free survival (DFS) and OS in those treated with adjuvant gemcitabine, and not 5-fluorouracil, suggesting that SPARC may have a role as a predictive marker." (PMID 27544129, 2016). "SPARC was also detectable in the pull down of heparin-binding proteins of conditioned medium of PSCs, but not of COLO-357 and PANC-1 pancreatic cancer cells." (PMID 19920824, 2010).
glioma (75 papers, 2004 to 2025). A benign or malignant brain and spinal cord tumor that arises from glial cells (astrocytes, oligodendrocytes, ependymal cells). "SPARC has already garnered interest as a multifaceted protein with a strong association with highly aggressive glioma." (PMID 35646664, 2022). "For example, SPARC-driven glioma cell survival and invasive capacity have been associated with increased activities of FAK and ILK kinases involving the phosphatidylinositol 3-kinase (PI3K)-Akt axis." (PMID 26248315, 2015). "SPARC is expressed in several types of brain tumours, and its expression in astrocytomas and gliomas is generally associated with increased invasion, angiogenesis, and a negative prognosis." (PMID 24551460, 2014). "The RFP cells expressed CD133, a marker frequently used to identify brain-tumor stem-like cells, as well as the glioma-associated, secreted protein SPARC, and the endothelial cell marker CD31, as revealed by confocal microscopy." (PMID 24282558, 2013). "On the contrary, it was shown that low SEMA3B expression associated with poorer OS in gliomas, but when associated with expression of two other genes, osteonectin/SPARC and doublecortex/doublecortin." (PMID 18781179, 2008). "HSA accumulation in U87MG glioma was associated with SPARC expression in vivo." (PMID 31695779, 2019). "Interestingly, the SLF was shown to oppose the synaptogenic action of full length Hevin and was found associated with SPARC in neovasculature of gliomas." (PMID 24551460, 2014). "High levels of SPARC are also associated with invasive meningioma, osteosarcoma and glioma." (PMID 23935929, 2013). "SPARC was associated with the invasiveness of meningiomas and gliomas." (PMID 20525171, 2010). "This protein, which phylogenetically shares many of the functions of SPARC, was also identified in another proteomic study of cystic fluid derived from high-grade glioma samples." (PMID 37627098, 2023). "As expected, the ZnPcS inflow was significantly decreased in the mouse brains transplanted with glioma cells in which the SPARC gene was knocked out, and it appeared to inflow at the control group level, which was not transplanted with U87 cells." (PMID 36945032, 2023). "In glioma with knockout SPARC, the amount of ZnPcS entering the glioma was reduced by 63.1%, indicating that it can target glioma through the SPARC pathway." (PMID 36945032, 2023). "The tumor epithelium and glioma cells overexpressed albumin-binding proteins such as SPARC and gp60." (PMID 37836018, 2023). "Albumin-binding ZnPcS was designed to pass through the BBB and bind to secreted protein acidic and rich in cysteine (SPARC), which is abundant in the glioma plasma membrane." (PMID 36945032, 2023). "In particular, ZnPcS with an amphiphilic structure was used to target gliomas overexpressing SPARC by strongly binding to albumin in situ." (PMID 36945032, 2023). "Secreted protein acidic and rich in cysteine (SPARC) is an extracellular glycoprotein expressed in gliomas and binds to albumin, suggesting that it plays an important role in tumor uptake of the ICG-HSA complex." (PMID 36614294, 2023). "SPARC protein is secreted by astrocytes and expressed by gliomas and malignant meningiomas, but in these last tumors its role has been recently challenged." (PMID 37627098, 2023). "SPARC has been found to be over-expressed in glioma and provides a mechanism for albumin-based drug delivery to the CNS." (PMID 37213306, 2023). "Albumin-based delivery systems have also been shown to interact with cell surface receptors such as SPARC and gp60, which are overexpressed on glioma cells and tumor endothelia." (PMID 37836018, 2023). "According to the findings, HSA was uptaken into the tumors, and SPARC contributed to its enhanced accumulation and improved its micro-distribution in gliomas." (PMID 37836018, 2023). "Researchers have conducted a study to investigate the accumulation of HSA in U87MG glioma cells through active SPARC-mediated targeting." (PMID 37836018, 2023).
glioma (continued). "SPARC increases the level of phosphorylation of AKT in gliomas through the PI3K/AKT pathway, significantly inhibiting EGF activity in ovarian cancer, and can activate GSK3β targets in adipocytes." (PMID 35211625, 2022). "In glioma, SPARC can suppress tumor growth but promote invasion and migration by regulating integrin and growth factor receptor-regulated kinases with their downstream effectors." (PMID 35646664, 2022). "SPARC expression is significantly upregulated in cells and stroma from a number of cancers, including glioma, breast and cervical melanoma, with oncogenic roles in cell growth, invasion and survival." (PMID 35869056, 2022). "In brain gliomas, SPARC is detrimental in that it promotes the survival and invasion of glioma cells." (PMID 36430810, 2022). "Gliomas highly express transferrin receptor and albumin-binding receptor SPARC, while M2 TAMs also highly express SPARC and mannose, therefore facilitating the dual-targeting role of these nanoparticles for both gliomas and M2 TAMs." (PMID 33790906, 2021). "Another marker for astrocytes and glial cells is the Secreted protein, acidic, and rich in cysteine (SPARC), which is also highly expressed in glioma." (PMID 34681783, 2021). "Previous studies have shown albumin-based nanocarriers to engage cell-surface receptors overexpressed in glioma cells and tumor vessel endothelium, SPARC, and gp6034,35." (PMID 33173024, 2020). "In glioma cells, IRE1 has been described to target the mRNA encoding the extracellular matrix protein SPARC." (PMID 32111004, 2020). "SPARC negatively regulates cell proliferation, angiogenesis and adhesion, but is increased in gliomas (grades II–IV)." (PMID 33383671, 2020). "Recently, Shi Q and his colleagues showed that downregulation of SPARC expression with siRNAs significantly decreased the invasion of glioma cells." (PMID 31897236, 2020). "CGP-based gene set identified in the present study suggests altered methylation in genes that are up-regulated in glioma cell lines after knockdown of SPARC gene by RNAi (FDR = 0.003)." (PMID 32583859, 2020). "HSA-based constructs often bind to albondin on the endothelium and SPARC in the tumor interstitium, thereby accumulating in and highlighting tumors, including brain tumors (glioma)." (PMID 32276437, 2020). "To investigate the HSA-dependent therapeutic effect of HSA–CDDP, we used two types of U87MG glioma cells that express SPARC differently." (PMID 33114661, 2020). "SPARC depletion in gliomas increased survival, and this increase was further improved when animals were treated with the standard chemotherapeutic temozolomide (TMZ)." (PMID 31062076, 2019). "We demonstrated that SPARC depletion in gliomas with elevated AKT activity improved the response to TMZ treatment and prolonged survival." (PMID 31062076, 2019). "We visualized HSA uptake in various cancer cells, especially glioma cells expressing more SPARC showed higher HSA uptake." (PMID 31695779, 2019). "By advanced ultramicroscopy for studying single-cell invasion in whole, undissected mouse brains, we show that gliomas require SPARC for invading into white matter structures." (PMID 31062076, 2019). "Our pre-clinical data are further supported by patient glioma samples, in which high AKT levels were associated with strong SPARC expression in tumor cells within both the invasive zone and the tumor bulk." (PMID 31062076, 2019). "Research about the interaction of tumor and microenvironment by SPARC is not well understood, so this topic has attracted much attention and is especially important in glioma." (PMID 31695779, 2019). "Because glioma has been reported to be high SPARC-expressing cancer in patients 27, we tested several glioma as well as other cancer cell lines." (PMID 31695779, 2019). "In this study, we first showed HSA accumulation in U87MG glioma by SPARC-mediated active targeting of HSA." (PMID 31695779, 2019).
glioma (continued). "In this study, we have shown that SPARC mediates HSA accumulation in U87MG glioma cells that express high levels of SPARC." (PMID 31695779, 2019). "High accumulation of FNR648-HSA in SPARC-expressing cells, especially in glioma cells, was observed." (PMID 31695779, 2019). "Based on these observations, we chose U87MG glioma to further elucidate the relationship between SPARC and HSA." (PMID 31695779, 2019). "Secreted protein acidic and rich in cysteine (SPARC), a matricellular protein, is strongly expressed in highly invasive gliomas." (PMID 31062076, 2019). "In pre-clinical mouse glioma models, we demonstrated that depleting SPARC and thus preventing white-matter invasion significantly prolonged survival and improved the treatment response to TMZ." (PMID 31062076, 2019). "In this study, we investigated the relationship between SPARC and HSA, and SPARC-mediated active targeting of HSA in U87MG glioma." (PMID 31695779, 2019). "All the albumin NPs showed colocalization with SPARC, indicating that the SPARC-mediated pathway was involved in the glioma-targeting delivery." (PMID 29732051, 2018). "Meanwhile, SPARC and TfRs were also overexpressed in the glioma cells, and SPARC and MRs overexpressed in TAM2." (PMID 29732051, 2018). "Despite the documented roles of TGFB1, SPARC and LAMA4 in GBM progression and invasion, only the SPARC protein was identified in the two clinical glioma EV preparations profiled here." (PMID 27770278, 2017). "It is known that SPARC is overexpressed in several invasive malignant tumors including meningioma, osteosarcoma and glioma." (PMID 23935929, 2013). "Silencing of CTGF in glioma cells and GSCs decreased the expression and phosphorylation of FAK and the expression of SPARC, two pathways that are implicated in cell migration." (PMID 23390502, 2013). "When the SPARC-expressing glioma cells were treated with TMZ, our results are consistent with previous reports that suggest SPARC is a therapeutic agent." (PMID 22480225, 2012). "We have found that SPARC promotes glioma migration and invasion, in part, through the upregulation of the p38 MAPK-MAPKAPK2 (MK2)-HSP27 signaling axis." (PMID 22480225, 2012). "As noted, SPARC increases invasion of glioma cells, but also has a suppressive effect on their growth." (PMID 22480225, 2012). "By suppressing tumour vascularity through suppression of VEGF expression and secretion, SPARC inhibited glioma growth." (PMID 22957090, 2012). "We therefore investigated the effects of SPARC with respect to TMZ as it is the current chemotherapy for glioma patients." (PMID 22480225, 2012). "We further demonstrated that SPARC promotes tumor cell migration and invasion in vitro, and we and others have demonstrated that SPARC promotes invasion in vivo, suggesting that it is a therapeutic target to prevent tumor invasion of gliomas." (PMID 22480225, 2012). "The studies using the primary human glioma cells lines indicate that in cells having high SPARC and HSP27 but low pAKT, targeting HSP27 does suppress survival by inducing apoptotic and autophagic signaling." (PMID 22480225, 2012). "The expression of SPARC has been positively correlated with the histological grade of tumor cells in bladder cancer, thyroid cancer, glioma and HCC." (PMID 22321704, 2012). "In glioma, SPARC inhibited tumour growth by altering its micro-environment and suppressing its angiogenesis through the inhibition of VEGF expression and secretion." (PMID 22957090, 2012). "In glioma, SPARC promotes invasion via upregulation of the p38 MAPK/MAPKAPK2/HSP27 signaling pathway, and promotes tumor cell survival by upregulating pAKT." (PMID 22480225, 2012). "The SPARC modulates glioma growth by altering the tumour microenvironment and suppressing tumour vascularity through suppression of VEGF expression and secretion." (PMID 20087345, 2010). "It has been reported that SPARC promotes glioma cell survival through Akt activation through integrin signaling under serum-free conditions." (PMID 20525171, 2010).